MIR3651 (microRNA 3651)
Synonyms: hsa-mir-3651; mir-3651
Gene: MicroRNA gene on chromosome 9 (92,292,458 to 92,292,547, reverse strand). Ensembl gene ENSG00000281156.
Gene Ontology:
Biological process: RNA processing
Cellular component: nucleolus